FPR3 (formyl peptide receptor 3)
Diseases named in the same sentence as FPR3 in open-access papers:
FPR3 is named in the same sentence as 21 diseases in open-access papers, as found by Europe PMC text mining. Sharing a sentence is not in itself a finding about the gene and the disease. The quoted sentences say what the papers report.
breast carcinoma (5 papers, 2020 to 2025). "A recent study identified FPR3 as a key immune-related biomarker for predicting poor prognosis of breast cancer, possibly playing an important role in the progression of breast cancer by modulating the immune microenvironment." (PMID 38817876, 2024). "The Kaplan-Meier survival curve (Data comes from TCGA) shows that the expression of FPR3 in breast cancer is negatively related to the survival of patients." (PMID 33679387, 2020). "FPR3 is highly expressed in a variety of cancers including different breast cancer subtypes, COAD cancer, and HNSC cancer." (PMID 33679387, 2020). "We further found that FPR3 is an independent hazard factor in the immune microenvironment of breast cancer, and its expression is accompanied by the activation of many pathways in cancer, highlighting the essential role of FPR3 in cancer progression." (PMID 33679387, 2020). "Overall, this study identifies FPR3 as a key immune-related intervention target, improving our understanding of the complex roles of the immune microenvironment in breast cancer progression." (PMID 33679387, 2020). "In summary, this study identified FPR3 as a key immune-related biomarker predicting a poor prognosis for breast cancer, revealing it as a promising intervention target for immunotherapy." (PMID 33679387, 2020). "As shown in both Oncomine and GEPIA databases, the expression of FPR3 in breast cancer is much higher than that in adjacent normal tissue." (PMID 33679387, 2020). "Current work demonstrated that FPR3 is a prognostic marker in breast cancer progression." (PMID 33679387, 2020). "The detailed mechanisms of FPR3 in breast cancer still require further investigation." (PMID 33679387, 2020).
glioma (3 papers, 2020 to 2024). A benign or malignant brain and spinal cord tumor that arises from glial cells (astrocytes, oligodendrocytes, ependymal cells). "In glioma, FPR3 emerged as a notable risk factor, with the prognostic model effectively forecasting patient results." (PMID 39445161, 2024). "These outcomes highlight a robust association between elevated FPR3 expression and aggressive features in gliomas." (PMID 39445161, 2024). "Our results imply a potential association of FPR3 with tumor immunity, indicating its viability as a prognostic indicator in glioma." (PMID 39445161, 2024). "Based on our findings, FPR3 has the strongest association with glioma." (PMID 39445161, 2024). "GSEA techniques were employed to identify signaling pathways associated with FPR3 in gliomas." (PMID 39445161, 2024). "In order to assess the prognostic significance of FPR3 in glioma, samples from TCGA and CGGA were categorized into groups based on their FPR3 expression levels relative to the median." (PMID 39445161, 2024). "The investigation demonstrated that glioma tissues exhibited significantly elevated levels of FPR3 expression in comparison to normal tissues (p < 0.001)." (PMID 39445161, 2024). "In conclusion, these findings indicate that FPR3 holds promise as a prognostic biomarker for assessing glioma patients." (PMID 39445161, 2024). "Our research successfully identified and confirmed the significance of FPR3 expression as a valuable and independent predictive indicator for glioma." (PMID 39445161, 2024). "This research investigated the levels of FPR3 and the presence of immune cells infiltrating glioma tissues in patients." (PMID 39445161, 2024). "The potential biological relevance of FPR3 was confirmed in glioma, and it was shown to have significant involvement in the processes of glioma growth, immune infiltration, and metastasis." (PMID 39445161, 2024). "The results consistently indicated an upregulation of FPR3 protein expression in glioma specimens compared to the paired adjacent specimens." (PMID 39445161, 2024). "FPR3 was previously identified as one of six immune-related genes in a study analyzing the expression and functionality of low-grade gliomas." (PMID 39445161, 2024). "A heatmap was created to visually represent the top 50 genes that exhibited significant correlation with FPR3 expression in gliomas." (PMID 39445161, 2024). "The predictive significance of FPR3 was evaluated independently in gliomas using data from TCGA and CGGA datasets, leading to the development of a prognostic nomogram." (PMID 39445161, 2024). "To obtain a more comprehensive understanding of FPR3’s involvement in gliomas, we conducted a examination of DEGs using GO and KEGG enrichment analyses." (PMID 39445161, 2024). "Meanwhile we explored the role of SIGLEC1 (also known as CD169) and FPR3 in the prognosis and immunotherapy of glioma and thought them would be new biomarkers and targets in diagnoses and treatment of glioma." (PMID 33408717, 2020). "The results revealed that the expression of CD163 and FPR3 were increasing in glioma, especially in GBM, the expression of P2RY12 was high in glioma, but more notable in LGG." (PMID 33408717, 2020). "In glioma, the Formyl peptide receptor (FPR, also called FPR1) can regulate the invasion, angiogenesis and growth of tumor, however, the function of FPR3 in glioma is still unclear." (PMID 33408717, 2020). "Therefore, we further analyzed FPR3 expression in glioma, its prognostic significance concerning immune infiltration, and performed functional analysis." (PMID 39445161, 2024). "The levels of FPR3 protein in glioma were verified using immunohistochemistry and Western blot." (PMID 39445161, 2024). "In glioma, FPR3 expression shows a positive correlation with immune infiltration, particularly involving immune cells linked to anti-tumor activity, such as regulatory T cells, central memory CD8 T cells, and macrophages, according to an analysis of cancer classifications in the database." (PMID 39445161, 2024).
glioma (continued). "Furthermore, FPR3 presence is related to the infiltration of diverse immune cells, possibly affecting the glioma immune microenvironment." (PMID 39445161, 2024). "However, accurately determining the specific role of FPR3 in regulating the microenvironment in gliomas is challenging." (PMID 39445161, 2024). "Immunohistochemistry and Western blot analysis confirmed FPR3 expression in gliomas." (PMID 39445161, 2024). "FPR3 and SIGLEC1 were high expression genes in glioma associated with grades and IDH status." (PMID 33408717, 2020). "In glioma patients, increased FPR3 expression may predict poorer outcomes." (PMID 39445161, 2024). "Similarly, high expression of FPR3 is associated with grade and IDH status in glioma." (PMID 37189838, 2023). "Through scRNA sequencing, we were able to identify FPR3 expression in malignant cells as well as immune cells like CD8Tex cells, dendritic cells (DC), and macrophages within BRCA, glioma, GBM, LIHC, NSCLC, and SKCM samples." (PMID 39445161, 2024). "In consideration of FPR3 expression is mainly in monocytes and relates with the grade, IDH status, and prognosis, it is very promising to be a novel biomarker for glioma." (PMID 33408717, 2020). "FPR3 correlated positively with immune checkpoint genes, particularly PD-1 and CD48, suggesting its potential regulation of diverse immunological checkpoints in gliomas." (PMID 39445161, 2024). "However, no protein expression information of FPR3 in brain or glioma was found in the database." (PMID 33408717, 2020). "However, the role of FPR3 and SIGLEC1 in glioma still not be explored." (PMID 33408717, 2020).
breast tumor (2 papers, 2020 to 2024). "We proposed that FPR3 may regulate the behaviors of tumor cells or immune cells through unspecified ligands in the breast tumor microenvironment." (PMID 33679387, 2020).
Allergy (1 paper, 2020). An allergy is an immune response or reaction to substances that are usually not harmful. "The identification of dectin‐1 as a key player in allergy to tropomyosins and the formyl peptide receptor 3 in allergy to lipocalins are outstanding examples of research into the mechanism of allergic sensitization." (PMID 32882057, 2020).
colorectal tumor (1 paper, 2017). "In this work, we found that the expression of FPR1, but not FPR2 or FPR3, was associated with colorectal tumor serosal invasion." (PMID 28724995, 2017).
diabetic nephropathy (1 paper, 2021). "Finally six Hub genes related to iron death in diabetic nephropathy were obtained, including FPR3, C3AR1, CD14, ITGB2, RAC2 and ITGAM." (PMID 34735495, 2021). "Hub genes (FPR3, C3AR1, CD14, ITGB2, RAC2 and ITGAM) related to iron death in diabetic nephropathy were obtained through gene expression differential analysis between different subtypes." (PMID 34735495, 2021). "There is no research to clarify the role of FPR3 in inflammation and immunity of diabetic nephropathy, but the intervention of FPR3 may become a new treatment strategy for diabetic nephropathy." (PMID 34735495, 2021).
endothelial dysfunction (1 paper, 2019). In vascular diseases, endothelial dysfunction is a systemic pathological state of the endothelium (the inner lining of blood vessels) and can be broadly defined as an imbalance between vasodilating and vasoconstricting substances produced by (or acting on) the endothelium. "Thus, our findings open the possibility of using synthetic FPR1 antagonists and FPR2/FPR3 agonists to resolve persistent inflammation and subsequent endothelial dysfunction in OSA." (PMID 31116781, 2019).
gastric cancer (1 paper, 2024). A primary or metastatic malignant neoplasm involving the stomach. "A recent study demonstrated that FPR3 inhibits the AKT/mTORC1 signaling pathway by modulating cellular calcium ion fluxes, thereby impeding the progression of gastric cancer." (PMID 39445161, 2024).
glioblastoma (1 paper, 2025). The most malignant astrocytic tumor (WHO grade IV). "We next tested whether the peptide f-MVPIKI and its derivatives could induce intracellular Ca2+ release in the human glioblastoma cell line U87-MG that is known to express FPR1, FPR3 and trace amounts of FPR239 (Supplement 2)." (PMID 40940450, 2025).
Hypertension (1 paper, 2019). The presence of chronic increased pressure in the systemic arterial system. "We speculate that human genetic variants of FPR3 and its under-expression may contribute to the development of the hypertension phenotype under chronic IHR stimuli in OSA syndrome." (PMID 31116781, 2019). "OSA patients with hypertension had decreased FPR2 expressions on neutrophil and FPR3 expressions of NK cell." (PMID 31116781, 2019). "In the present study, we found that FPR3 expressions of both M1 monocyte and NK cell were decreased in OSA patients and the latter was further decreased in those with hypertension." (PMID 31116781, 2019). "We have found a link of FPR1 over-expression and FPR2 under-expression on blood neutrophil along with defective production of LXA4/RvD1, as well as FPR3 insufficiency of M1 monocyte, M2a monocyte, and NK cell, to OSA and its adverse consequences, including hypertension and EDS." (PMID 31116781, 2019). "Furthermore, we found increased FPR1/FPR2 ratio and insufficiency of FPR2 and FPR3 in the OSA patients with EDS and hypertension phenotypes, respectively, while long-term CPAP treatment decreased FPR1 expression and FPR1/FPR2 expression ratio, and increased FPR3 and FPR2 expression." (PMID 31116781, 2019).
placental insufficiency (1 paper, 2020). Failure of the placenta to deliver an adequate supply of nutrients and oxygen to the fetus. "Future studies should elucidate whether the downregulated LGALS1 and FPR3 expressions in FGR are angiogenesis-modulating regulators leading to placental insufficiency-induced FGR or whether the expression of these genes can be used as a biomarker for increased cardiovascular risk." (PMID 33256815, 2020).
viral infections (1 paper, 2025). "Finally, we identified a surprisingly large number of FPR3 activators, which argues for an unrecognized role of FPR3 during viral infections." (PMID 40703440, 2025). "In addition, these results suggest that FPRs and particularly FPR3 may play a previously unnoticed role in many different types of viral infections through an interaction with envelope protein fragments from miscellaneous virus." (PMID 40703440, 2025).
tumor (17 papers, 2017 to 2025). "Particularly attractive are the immunomodulatory role of FPR2 by regulating proinflammatory and anti-inflammatory activities and the association of FPR3 with tumor immunity, indicating its availability as a prognostic biomarker in cancer." (PMID 40103822, 2025). "Our research has demonstrated a notable elevation in FPR3 levels across multiple tumor types, closely linked to unfavorable patient outcomes." (PMID 39445161, 2024). "FPR1 and FPR3 are macrophage gene markers, participating in neutrophil recruitment 71 and tumor-associated inflammation." (PMID 34326696, 2021). "Similarly, the strong association of FPR3 with macrophages emphasized its essential role in shaping the tumor microenvironment." (PMID 40394037, 2025). "FPR3 genetic mutation in TCGA tumour samples revealed unique patterns." (PMID 39445161, 2024). "In this investigation, we scrutinized FPR3’s expression profiles, genetic alterations, prognostic significance, immune-related characteristics, methylation status, tumor mutation burden (TMB), and microsatellite instability (MSI) across different types of cancer." (PMID 39445161, 2024). "In contrast, the FPR3/NFATc1/NOTCH3 axis exerts tumor-suppressive effects in diffuse-type GC by modulating calcium flux: FPR3 activation restricts NFATc1 nuclear translocation, downregulating NOTCH3-AKT/mTOR signaling and suppressing stemness." (PMID 40977684, 2025). "FPR3 expression was elevated in the majority of tumor tissues, with a marked decrease in LUSC, ALL, and ACC compared to normal tissues." (PMID 39445161, 2024). "Tumor immunotherapy, particularly the modulation of immune checkpoints by suppressing FPR3 expression, has garnered significant attention in our research." (PMID 39445161, 2024). "We found that LGALS9_CD44, MIF_TNFRSF14, CD47_SIRPG, MDK_LRP1 and LGALS9_HAVCR2, CD74_COPA, C3_C3AR1, ANXA1_FPR3 interactions were upregulated in both ductal-tumor and malignant cells versus ductal-normal." (PMID 35087839, 2021). "FPR3 overexpression suppresses tumor progression; potential therapeutic agonist." (PMID 40977684, 2025). "Moreover, compared with ductal-normal and ductal-tumor cells, CD55_ADGRE5, CD99_PILRA, ANXA1_FPR3 interactions were drastically upregulated in the malignant cells." (PMID 35087839, 2021). "A subset of GPCRs is overexpressed in many tumors, e.g., FPR3 in 38 of the 45 tumor categories." (PMID 31765370, 2019). "Therefore, it is necessary to understand the specific properties of the unknown ligand for FPR3, and to make an in-depth analysis of the signaling pathways activated in tumor cells and immune cells." (PMID 33679387, 2020). "For example, in TAMs, gene expression of FPR3, PLAUR, and LRP1, the receptor genes interacting with tumor cells, was correlated with ligand genes interacting with CD8+ T cells including C5AR1." (PMID 38002057, 2023). "Ac2-26 has been shown to regulate leukocytes and other tumor cell migratory events through interactions with formyl peptide receptors (FPRs), and thus we examined the expression of FPR1, FPR2, and FPR3 in BC cells by RT-qPCR." (PMID 36414640, 2022). "In addition, high levels of HCST, C3AR1, GBP4, LY96, ANKRD22, FPR3 and FCGR2A, have also been related to immune activation and/or inflammatory response in tumours; however, their role in basal-like breast malignancies are yet to be uncovered." (PMID 28351365, 2017).
cancer (7 papers, 2016 to 2025). A tumor composed of atypical neoplastic, often pleomorphic cells that invade other tissues. "In eight cancers, FPR3 expression was positively linked with TMB, with THYM, OV, LGG, and COAD showing the most significant associations." (PMID 39445161, 2024). "As annotated in the “pathways in cancer”, high FPR3 expression associates with many pathways that promote tumorigenesis and development, such as the VEGF signaling pathway, MAPK signaling pathway, and PI3K-AKT signaling pathway." (PMID 33679387, 2020). "FPR3 has potential as both a diagnostic marker for specific types of cancer." (PMID 39445161, 2024). "Among the five cancer types, SKCM, UCEC, COADREAD, LIHC, and LUAD, “Mutation” occupied the most common type of FPR3 alterations." (PMID 39445161, 2024). "Formyl peptide receptor 3 (FPR3) is known to have implications in the progression of various cancer types." (PMID 39445161, 2024). "Although FPR3 has been examined in specific malignancies, it remains excluded from extensive cancer analyses." (PMID 39445161, 2024). "Numerous cancer types demonstrated high correlations between FPR3 expression and both immune checkpoint molecules and TMB levels." (PMID 39445161, 2024). "This research aimed to evaluate the prognostic impact, genetic alterations, and FPR3 expression across various cancer types." (PMID 39445161, 2024). "In numerous cancer types, heightened FPR3 expression correlated with adverse outcomes, immune cell infiltration, immune checkpoints, TMB, and MSI." (PMID 39445161, 2024). "Since FPR3 has a potential cancer-promoting effect in various cancers, including GBM, and the oncogenic role of FPR3 in GBM were then tested in vitro in GBM cell lines." (PMID 39445161, 2024). "Overall, our comprehensive analysis of FPR3 alterations in various cancers utilizing the TCGA dataset and COSMIC database revealed intriguing insights." (PMID 39445161, 2024). "We further screened the activated ligand-receptor pairs between ductal cells and these two stroma-cell types and defined several cancer-associated pairs, such as EGFR/TGFB1, ANXA1/FPR3, EREG/EGFR, and ICAM1/AREG." (PMID 34326696, 2021). "Our pan-cancer analysis revealed that FPR3 is upregulated in 25 tumors, including GBM and LGG." (PMID 39445161, 2024). "Similarly, the expression of the ANXA1/FPR1 or FPR3 pair was upregulated from ductal cell-myeloid cell to cancer cell-myeloid cell communication." (PMID 34326696, 2021). "The top two enriched pathways in the high expression group of FPR3 were “pathways in cancer” and “cytokine-cytokine receptor interaction”, implying that FPR3 upregulation may lead to alterations in cancer-related pathways and cytokine-based immune regulations." (PMID 33679387, 2020). "We used TIMER to evaluate the expression of FPR3 in pan-cancer." (PMID 33679387, 2020). "Thus, activation of FPR3 may regulate various malignant behaviors of cancer cells, including proliferation, avoidance of apoptosis, and sustained angiogenesis, via its G-protein-coupled signaling cascades." (PMID 33679387, 2020). "In the “pathways in cancer”, PIK3R5, SPI1, and CSF1R are most relevant to FPR3 expression (Figures 7A1–A3)." (PMID 33679387, 2020). "N‐formyl peptide receptors (FPR1, FPR2, and FPR3) play key roles in the regulation of inflammatory processes, and recently, it was demonstrated that FPR1 and FPR2 have a dual role in the progression/suppression of some cancers." (PMID 34148303, 2021).
infection (2 papers, 2018). The state of being infected such as from the introduction of a foreign agent such as serum, vaccine, antigenic substance or organism. "FPR3 has been implicated in the sensing of infection-associated olfactory cues and in the response to bacterial endotoxin stimuli." (PMID 29544524, 2018).
FPR3 also shares sentences with these, for which no sentence is quoted: cardiovascular disease (2 papers); colorectal cancer (1); COVID-19 (1); diabetes mellitus (1); neurodegenerative disease (1); sleep disordered breathing (1).